LAMP2 (lysosome associated membrane protein 2)
Diseases named in the same sentence as LAMP2 in open-access papers (continued):
Sharing a sentence is not in itself a finding about the gene and the disease.
hypertrophic cardiomyopathy (17 papers, 2011 to 2026). A condition in which the myocardium is hypertrophied without an obvious cause. "Another urgent task is expanding LAMP2 mutation screening in male patients with unexplained cardiomyopathy – particularly those with hypertrophic cardiomyopathy (HCM) and elevated CK." (PMID 41560058, 2026). "We presented a family with a novel splice-altering mutation (LAMP2 c.741+2T>C) in 3'-splice site of exon 5 with cardiac-only symptoms (frequent ventricular tachycardia, intraventricular block, and hypertrophic cardiomyopathy)." (PMID 34901223, 2021). "We describe a specific family with a novel pathogenic splice-altering mutation in the LAMP2 gene (c.741+2T>C) with cardiac-only symptoms (frequent ventricular tachycardia, intraventricular block, and hypertrophic cardiomyopathy)." (PMID 34901223, 2021). "We found a novel frameshift mutation, a hemizygous mutation (c.1052delG) in exon 8 of LAMP2, identified as presenting the hypertrophic cardiomyopathy (HCM) phenotype." (PMID 33933120, 2021). "Few studies focus on the evaluation for hypertrophic cardiomyopathy of Lamp2-deficient hemizygote male mice." (PMID 29720683, 2018). "Mutations in the LAMP2 gene have been identified in patients with hypertrophic cardiomyopathy, and the gene product mediates adherence of PBMCs to the vascular endothelium." (PMID 21356094, 2011). "The patient's early onset hypertrophic cardiomyopathy was likely determined by the haploinsufficiency of LAMP2 and the XCI inactivation pattern." (PMID 37288668, 2023). "Lamp2‐knockout mice show hypertrophic cardiomyopathy with accumulated autophagic vacuoles." (PMID 36562207, 2023).
lysosomal storage disorder (16 papers, 2005 to 2026). "Patients harboring sequence variants in genes that lead to lysosomal storage disease, such as lysosomal-associated membrane protein 2 (LAMP2), also manifest HCM phenotypes." (PMID 33329049, 2020). "In contrast, a marked staining of LAMP2, an established marker for lysosomal storage disorder (LSD) was increased." (PMID 38053930, 2023). "Since protein levels of LAMP2 increase also in lysosomal storage diseases such as neuronal ceroid lipofuscinosis or after treatment with lysosomotropic drugs, these results suggest that the endosomal/lysosomal pathway is also affected by Tam." (PMID 31455323, 2019). "High power electron micrographs revealed the presence of Lipid Whorls (LW) that are implicated in lysosomal storage disease and cholesterol accumulation in degenerating neurons within the CA3 and subiculum of LAMP-2-deficient mice." (PMID 25637286, 2015). "LAMP-2 has been reported to be increased in several lysosomal storage disorders as a general response to decreased lysosomal clearance, but has not previously been indicated as upregulated in AD." (PMID 24101586, 2014). "Imaging LAMP1 and LAMP2 revealed lower signals in T1D α cells, but a higher LAMP1/LAMP2 ratio, suggestive of lysosomal disorder." (PMID 41026524, 2025).
Obesity (12 papers, 2017 to 2025). Accumulation of substantial excess body fat. "It was demonstrated that LAMP2-deficient mice were protected against obesity, lipid accumulation, as well as hyperinsulinemia and hyperglycemia induced by a high-fat diet." (PMID 29977307, 2018). "LAMP‐2–dependent fusion and degradation processes of autophagosomes are involved in the pathogenesis of obesity‐related diabetes." (PMID 41476994, 2025). "Moreover, genes involved in lysosomal biogenesis and phagocytosis including Atp6v1b2, Atp6v0d2, Lipa, and Lamp2 were also reported to be induced in the ATMs in obesity." (PMID 40244655, 2025). "Lamp2 is suppressed by miR-487-5p, which has been found at higher levels in subjects with obesity." (PMID 32907629, 2020). "However, obese frailty resulted in a significant decrease in LAMP-2 expression, suggesting that it may regulate LAMP-2 through mechanisms affecting Smad2/3, FoxO3a, and P62 due to the combined effects of frailty syndromes and obesity." (PMID 39382189, 2024). "Interestingly, LAMP-2 down-regulation in PBMCs cultured with ASCEMS may be a novel mechanism that connects obesity and inflammation in EMS horses." (PMID 30356025, 2018). "Although no direct evidence has shown the implication of this miRNA in the vasculature, because Lamp2 is so crucially involved vascular function and integrity, we believe that we may gain some important insights by exploring this mechanism in the context of obesity-induced endothelial dysfunction." (PMID 32907629, 2020). "While aging is associated with a decline in autophagic flux due to decreased LAMP-2 expression, our data showed no significant changes in LAMP-2 expression in pure frailty, obesity, or obese frailty compared with the control group." (PMID 39382189, 2024).
pancreatitis (11 papers, 2013 to 2026). Inflammation of the pancreas. "Lysosome-associated membrane protein (LAMP) is an important component of lysosomes, and LAMP-2-deficient mice can develop spontaneous pancreatitis." (PMID 38605381, 2024). "Similar results were obtained for LAMP-2 deficient mice (that are deficient in their autophagic and lysosomal activity in all tissues), which are also highly susceptible to LPS-induced pancreatitis." (PMID 33087696, 2020). "In addition, certain vacuole-associated proteins, including LC3 protein, lysosomal-associated membrane protein (LAMP)-1, and LAMP-2 in autophagic vacuoles, have been revealed to contribute greatly to the modulation of pancreatitis." (PMID 39403146, 2024). "In addition, we and others have shown that genetic intervention leading to the local removal of essential autophagy genes such as autophagy-related 5 and 7, Atg5, Atg7, or lysosomal-associated membrane protein-2 (Lamp2) promotes the development of pancreatitis in rodents." (PMID 33087696, 2020). "We have shown that human pancreatitis is associated with disabled autophagic ATG7 and ATG5, as well as a reduction of LAMP2 protein expression, impairing acinar cell autophagy signaling." (PMID 33087696, 2020). "Phenotypically, similar to Lamp2−/− mice, Gal-9−/− mice also exhibited large autophagic vacuoles with partially digested materials in pancreas, decreased acinar cell homeostasis, and spontaneous pancreatitis." (PMID 32855403, 2020). "Interestingly, mice with defective lysosomal function by genetic deletion of LAMP2 also developed spontaneous pancreatitis." (PMID 31987928, 2020). "A decreased level of LAMP-2 was reported in LPS-induced experimental pancreatitis in rat54." (PMID 25797357, 2015). "Genetic modifications of core autophagy-related proteins like Atg5, Atg7, or LAMP2 in the pancreas lead to severe acinar cell degeneration, exocrine pancreas atrophy, fibrosis, inflammation, and cellular damage, highlighting autophagy impairment’s role in exacerbating pancreatitis severity." (PMID 39403146, 2024). "Moreover, loss of LAMP-2 does not preclude initiation of pancreatitis as LAMP-2 null mice developed acute pancreatitis upon caerulein stimulation questioning again the role of lysosomes for initiation of acute pancreatitis." (PMID 38709385, 2024). "Therefore, phenotypical correlations in Gal-9 and Lamp2 deficiency with respect to IBD, pancreatitis, and EIMs might support Gal-9-Lamp2 axis as a potential therapeutic target for these disorders and therefore is worth further investigation in animal models or human subjects." (PMID 32855403, 2020).
prostate carcinoma (11 papers, 2011 to 2024). A carcinoma that arises from epithelial cells of the prostate gland. "It was discovered that SFN therapy boosted the levels of the crucial autophagy regulators HSP90AA1 and UVRAG as well as the lysosome-associated membrane protein 2 (LAMP2) mRNA and protein in human prostate cancer cells." (PMID 38902597, 2024). "We further found that LAMP2 was still significantly associated with OS in multivariate Cox regression (HR = 0.095, p = 0.028), indicating its prognostic value in prostate cancer." (PMID 36741911, 2023). "Furthermore, we found immune infiltration of various immune cells significantly correlated with LAMP2 expression in prostate cancer and identified multiple microRNAs associated with LAMP2 expression in prostate cancer." (PMID 36741911, 2023). "In addition, we found that the methylation level of LAMP2 in prostate cancer was significantly associated with cancer and identified eight methylation sites for LAMP2." (PMID 36741911, 2023). "Furthermore, we analyzed and identified multiple microRNAs associated with LAMP2 expression in prostate cancer." (PMID 36741911, 2023). "In addition, we found that the methylation level of LAMP2 in prostate cancer was significantly associated with cancer and identified 8 methylation sites for LAMP2." (PMID 36741911, 2023). "Taken together, LAMP2-associated abnormalities in lipid metabolism and related signaling networks might play important roles in mechanisms of prostate cancer invasion and progression." (PMID 36741911, 2023). "All of these results suggested that the ferroptosis-related LAMP2 played an important role in progression and prognosis in prostate cancer." (PMID 36741911, 2023). "On this basis, we found immune infiltration of various immune cells significantly correlated with LAMP2 expression in prostate cancer." (PMID 36741911, 2023). "In conclusion, we compared differentially expressed genes between localized prostate cancer and metastatic CRPC and identified ferroptosis related gene LAMP2 as a potential biomarker with prognostic value for prostate cancer." (PMID 36741911, 2023). "We evaluated the promoter methylation level of LAMP2 in prostate cancer using the UALCAN database and found prostate cancer presenting a significantly decreased level." (PMID 36741911, 2023). "Compared to other autophagy related genes, LAMP2 was the best prognostic indicator and treatment target for prostate cancer patients." (PMID 37986192, 2023). "Other experimental investigations demonstrated that sulforaphane therapy promotes the expression of a lysosome-associated membrane protein 2 (LAMP2), which decreases sulforaphane’s capacity to trigger apoptotic cell death, at least in prostate cancer." (PMID 36295538, 2022). "This statement was supported by data showing that the silencing of LAMP2 by siRNAs led to a radiosensitization of prostate cancer cell lines." (PMID 33718194, 2021). "It will be interesting to investigate the expression levels of LAMP2 in tumors of this prostate cancer animal model to elucidate its possible role in tumor progression, and extend these studies to other NE prostate cancer models such as xenografts." (PMID 27627761, 2016). "The exosomal (CD9- CD81-SCARB2) (average enrichment 2.40) and lysosomal (CTSD- LAMP2- CTSZ- SPNS1- PSAP) (average enrichment 4.15) proteins were also enriched in exosomes from prostate cancer patients." (PMID 26196085, 2015). "In complex signaling networks of ferroptosis, the effect of LAMP2 on prostate cancer could be subject to complex regulation, and these should be corroborated and validated by further experiments." (PMID 36741911, 2023). "Jamali’s study showed that the expression of LAMP2 was significantly reduced in prostate cancer tissue and could trigger lysosomal membrane permeability, sensitizing cancer cells to lysosomal pathway mediated death." (PMID 37986192, 2023). "Ferroptosis-related gene LAMP2 is a potential biomarker with prognostic value for prostate cancer." (PMID 36741911, 2023).
prostate carcinoma (continued). "LAMP2 could thus be a potential biomarker and potential target for NE prostate cancer." (PMID 27627761, 2016). "We performed survival analysis and Cox regression for these genes and identified LAMP2 with significantly prognostic values in overall survival (OS) and disease-specific survival (DSS) of prostate cancer." (PMID 36741911, 2023). "Subsequently, we performed survival analysis and Cox regression for these genes and identified LAMP2 with significantly prognostic values in OS and DSS of prostate cancer." (PMID 36741911, 2023). "In the AR-independent prostate cancer PC-3 cells, a clear co-localization of androgen-BODIPY-conjugate- and LAMP-2-derived fluorescence signals was evident, indicating a lysosomal accumulation of these conjugates." (PMID 36835012, 2023). "Furthermore, data query showed that LuCaP 49 was CD57+ (B3GAT1; a marker associated with cells showing neuroendocrine differentiation), CD44-, CD107b+ (LAMP2, expressed by many prostate cancer cell types), CD10-, CD133+; LuCaP 35 was CD57-, CD44-, CD107b+, CD10+, CD133-." (PMID 21605402, 2011). "In addition, a recent in silico approach showed that the expression of LAMP2 was decreased in prostate cancer tissues as compared to normal prostate tissues, indicating that the expression level of LAMP2 could act as a regulatory element in cancer progression." (PMID 33718194, 2021).
colon carcinoma (10 papers, 2013 to 2025). "In colon cancer, LAMP2 is differentially expressed and has specific diagnostic value in the early stage of colon cancer as a molecular marker." (PMID 34124097, 2021). "Spheroids of p-glycoprotein doxorubicin-resistant MCF-7 cells (MCF-DOX) and HCT-116 colon cancer cells were also stained with LAMP2 and we obtained the same results." (PMID 26658462, 2015). "LAMP2 has been reported as an adhesive glycoprotein that participates in the processes of invasion and metastasis of melanoma, colon cancer, or fibrosarcoma cells." (PMID 24244679, 2013). "Indeed, lysosomal membrane proteins, LAMP-1 and LAMP-2, have been identified in Colo-205 cell lines as E-selectin ligands and their expression levels mediated colon cancer cells adhesion to E-selectin." (PMID 33167483, 2020). "In human metastasizing melanoma, fibrosarcoma, ovarian, and colon carcinoma cells, LAMP-1 and LAMP-2 were found to serve as GAL-1- and GAL-3-binding partners." (PMID 37898403, 2023). "By flow cytometry, GAL-3 was shown to bind LAMP-1 and LAMP-2 at the surface of A2058 melanoma, HT1080 fibrosarcoma, and CaCo-2 colon carcinoma cells." (PMID 37898403, 2023). "In contrast, hypoxia might also stimulate autophagy in colon cancer cells through the modulation of the translation of the highly conserved lysosomal glycoproteins PSAP and LAMP2, which in turn increase mitophagy and thus protect tumor cells." (PMID 39762799, 2025). "Using affinity chromatography on GAL-1-agarose columns and immunoprecipitation, LAMP-1 and LAMP-2 were first identified as candidate GAL-1 receptors in Chinese Hamster Ovary (CHO), human A121 ovarian carcinoma and butyrate-differentiated KM12 colon carcinoma cell membrane extracts." (PMID 37898403, 2023). "In colon cancer, the E-selectin ligands identified so far are HCELL, carcinoembryonic antigen (CEA), podocalyxin-like protein (PCLP), LAMP-1 (lysosomal membrane glycoprotein-1) and LAMP-2." (PMID 33167483, 2020).
Parkinson disease (10 papers, 2015 to 2025). A progressive degenerative disorder of the central nervous system characterized by loss of dopamine producing neurons in the substantia nigra and the presence of Lewy bodies in the substantia nigra and locus coeruleus. "Previous research into the physiology or diseases associated with LAMP-2 primarily focused on aging, renal hypertrophy, and neurodegenerative diseases such as Parkinson’s disease and Alzheimer’s disease." (PMID 36830954, 2023). "In Parkinson’s disease, upregulation of Pellino1 by α-synuclein leads to the degradation of lysosomal-associated membrane protein-2 (LAMP2) and the buildup of autophagy with decreased autophagy flux by microglial exosomes." (PMID 35197966, 2022). "In neuropathology, LAMP2 concentration has been reported to be decreased in the patient’s cerebrospinal fluid (CSF) of Parkinson’s disease and increased in patients with Alzheimer’s." (PMID 36980307, 2023). "LAMP2 is ubiquitously expressed in the central nervous system and has been reported involved in the development of Parkinson’s disease and Alzheimer’s disease." (PMID 35633787, 2022). "LAMP-2A, one specific LAMP-2 isoform, was proposed to be important for the lysosomal degradation of selective proteins involved in neurodegenerative diseases such as Huntington’s and Parkinson’s disease." (PMID 25637286, 2015). "Moreover, treadmill training has been shown to upregulate lysosomal proteins (LAMP2 and cathepsin L) in Parkinson’s disease, implying that treadmill training increased the activities of the lysosome to fuse with the autophagosome and destroy dysfunctional mitochondria in neural cells." (PMID 34440215, 2021).
Sepsis (10 papers, 2015 to 2025). Sepsis is defined as life-threatening organ dysfunction caused by a dysregulated host response to infection. "The autophagy level is significantly inhibited in septic patients with acute respiratory distress syndrome, and autophagy-associated proteins LC3II, Beclin-1, RAB7, LAMP2, and p62 have good value for the diagnosis and prognosis evaluation of sepsis comorbid with acute respiratory distress syndrome." (PMID 35371338, 2022). "ROC analysis results show that the most valuable autophagy-related protein that predicts the death of sepsis sufferers with ARDS is still LAMP2." (PMID 35371338, 2022). "Age, CRP, PCT, APACHE II, SOFA, LC3II, Beclin-1, RAB7, LAMP2, and p62 are related to the death of patients with sepsis and ARDS." (PMID 35371338, 2022). "In conclusion, the autophagy level is significantly inhibited in sepsis patients with ARDS, and autophagy-associated proteins LC3II, Beclin-1, RAB7, LAMP2, and p62 have good value for the diagnosis and prognosis evaluation of sepsis patients with ARDS." (PMID 35371338, 2022). "The expression of LC3II, Beclin-1, RAB7, and LAMP2 in sepsis patients with ARDS was significantly reduced; p62 was significantly increased, which suggests that autophagy was inhibited in patients with sepsis and ARDS." (PMID 35371338, 2022). "In the present study, levels of the LAMP-2 and Rab7 proteins were significantly decreased in mice with sepsis-induced liver injury, but levels of the cathepsin B protein were not changed." (PMID 30154452, 2018). "Moreover, the levels of autophagy-related proteins LC3II, Beclin-1, Rab7, Lysosomal Associated Membrane Protein 2 (LAMP2) and p62 had good value in the diagnosis and prognosis of ARDS patients due to sepsis." (PMID 36059534, 2022). "Furthermore, staining for the LC3-II protein was significantly increased upon overexpression of HIPK2, and LAMP-2 expression was restored by overexpression of HIPK2 in the livers of mice with sepsis." (PMID 30154452, 2018). "Key genes identified among these, such as FARSA, SVIL, LAMP2, and COL12A1, were found to be influenced by exercise in both burns and sepsis, suggesting their potential roles in exercise-mediated recovery processes." (PMID 40028316, 2025). "As shown, LAMP2, RAB7, LC3II, p62, and Beclin-1 predicted the AUC of death in sepsis patients with ARDS: 0.922, 0.833, 0.807, 0.745, and 0.708, respectively." (PMID 35371338, 2022). "Further ROC curve analysis results showed that autophagy-related proteins have a higher ability to recognize sepsis with ARDS, and the best one was LAMP2, which had a specificity of 91.46%." (PMID 35371338, 2022). "The AUCs of LAMP2, p62, RAB7, LC3II, and Beclin-1 for the diagnosis of sepsis with ARDS are 0.853, 0.773, 0.746, 0.728, and 0.650, respectively." (PMID 35371338, 2022). "We found that the level of LAMP-2 was not significantly different between the groups after sepsis induction." (PMID 33981237, 2021). "Although Beclin1, Atg7, and Atg12 in the Sepsis group were all slightly higher than the SFP group (p < 0.05), Unc-51-like autophagy activating kinase (Ulk1), Atg5, Atg8l, and Lamp2 were not different." (PMID 37106730, 2023). "Western blot outcomes revealed that in the peripheral blood monocytes of sepsis sufferers with ARDS, the relative expression levels of LC3II, Beclin-1, RAB7, and LAMP2 were remarkably lower in contrast to the non-ARDS group (P < 0.05)." (PMID 35371338, 2022).